SNW1 (SNW domain containing 1)
Description:
Involved in pre-mRNA splicing as component of the spliceosome. As a component of the minor spliceosome, involved in the splicing of U12-type introns in pre-mRNAs (Probable). Required for the specific splicing of CDKN1A pre-mRNA; the function probably involves the recruitment of U2AF2 to the mRNA. May recruit PPIL1 to the spliceosome. May be involved in cyclin-D1/CCND1 mRNA stability through the SNARP complex which associates with both the 3'end of the CCND1 gene and its mRNA. Involved in transcriptional regulation. Modulates TGF-beta-mediated transcription via association with SMAD proteins, MYOD1-mediated transcription via association with PABPN1, RB1-mediated transcriptional repression, and retinoid-X receptor (RXR)- and vitamin D receptor (VDR)-dependent gene transcription in a cell line-specific manner probably involving coactivators NCOA1 and GRIP1. Is involved in NOTCH1-mediated transcriptional activation. Binds to multimerized forms of Notch intracellular domain (NICD) and is proposed to recruit transcriptional coactivators such as MAML1 to form an intermediate preactivation complex which associates with DNA-bound CBF-1/RBPJ to form a transcriptional activation complex by releasing SNW1 and redundant NOTCH1 NICD. (Microbial infection) Is recruited by HIV-1 Tat to Tat:P-TEFb:TAR RNA complexes and is involved in Tat transcription by recruitment of MYC, MEN1 and TRRAP to the HIV promoter. (Microbial infection) Proposed to be involved in transcriptional activation by EBV EBNA2 of CBF-1/RBPJ-repressed promoters.
Synonyms: SKIIP; SKIP; NCoA-62; Prp45; PRPF45; Bx42; SKIP1; FUN20
Tractability: Small molecule: a structure with a bound ligand is known. PROTAC: UniProt records ubiquitination sites on it; ubiquitination databases record sites on it; its protein half-life has been measured.
Gene: Protein-coding gene on chromosome 14 (77,717,599 to 77,761,207, reverse strand). Ensembl gene ENSG00000100603.
Subcellular location: Nucleus
Subcellular location (Human Protein Atlas): Nucleoplasm; Cytosol
Pathways (Reactome):
Signal Transduction: Downregulation of SMAD2/3:SMAD4 transcriptional activity; NOTCH1 Intracellular Domain Regulates Transcription; NOTCH3 Intracellular Domain Regulates Transcription; NOTCH4 Intracellular Domain Regulates Transcription; Pre-NOTCH Transcription and Translation
Developmental Biology: Differentiation of naive CD4+ T cells to T helper 2 cells (Th2 cells); Formation of paraxial mesoderm; Regulation of gene expression in late stage (branching morphogenesis) pancreatic bud precursor cells
Disease: Constitutive Signaling by NOTCH1 HD+PEST Domain Mutants; Constitutive Signaling by NOTCH1 PEST Domain Mutants; Dengue Virus-Host Interactions
Gene expression (Transcription): Notch-HLH transcription pathway; RUNX3 regulates NOTCH signaling
Metabolism of RNA: mRNA Splicing - Major Pathway
Gene Ontology:
Molecular function: enzyme binding; Notch binding; nuclear androgen receptor binding; nuclear receptor binding; nuclear retinoic acid receptor binding; nuclear vitamin D receptor binding; protein binding; RNA binding; SMAD binding; transcription coactivator activity; transcription corepressor activity
Biological process: cellular response to retinoic acid; host-mediated activation of viral transcription; mRNA splicing, via spliceosome; negative regulation of DNA-templated transcription; negative regulation of transcription by RNA polymerase II; positive regulation of mRNA splicing, via spliceosome; positive regulation of transcription by RNA polymerase II; positive regulation of transforming growth factor beta receptor signaling pathway; positive regulation of vitamin D receptor signaling pathway; regulation of retinoic acid receptor signaling pathway; regulation of vitamin D receptor signaling pathway; retinoic acid receptor signaling pathway; mRNA stabilization; positive regulation of neurogenesis; regulation of transcription by RNA polymerase II
Cellular component: catalytic step 2 spliceosome; cyclin/CDK positive transcription elongation factor complex; nuclear matrix; nuclear speck; nucleoplasm; nucleus; post-mRNA release spliceosomal complex; post-spliceosomal complex; spliceosomal complex; U12-type catalytic step 2 spliceosome; U2-type catalytic step 1 spliceosome; U2-type catalytic step 2 spliceosome
Genetic constraint (gnomAD): Loss-of-function variants: 5 observed, 48.71 expected, observed/expected ratio (o/e) 0.1, 90% interval 0.053 to 0.22. The upper end of that interval is the gene's LOEUF score, 0.22, which puts it in group 1 of 6, group 1 being the genes least tolerant of losing a copy. Missense variants: 342 observed, 524.16 expected, observed/expected ratio (o/e) 0.65, 90% interval 0.6 to 0.71. Synonymous variants: 153 observed, 175.41 expected, observed/expected ratio (o/e) 0.87, 90% interval 0.76 to 1.
Homologues: Orthologues: macaque SNW1 (100% identical), dog SNW1 (99% identical), pig SNW1 (99% identical), rabbit SNW1 (99% identical), mouse Snw1 (99% identical), guinea pig SNW1 (99% identical), rat Snw1 (99% identical), tropical clawed frog snw1 (89% identical), zebrafish snw1 (85% identical), Drosophila melanogaster Bx42 (62% identical), Caenorhabditis elegans skp-1 (56% identical).
Diseases named in the same sentence as SNW1 in open-access papers:
SNW1 is named in the same sentence as 13 diseases in open-access papers, as found by Europe PMC text mining. Sharing a sentence is not in itself a finding about the gene and the disease. The quoted sentences say what the papers report.
breast carcinoma (3 papers, 2015 to 2020). "For example, SNW1 overexpression is linked to high tumor grade and accelerated cell proliferation in breast cancer, and to poor prognosis in urinary bladder cancer, hepatocellular carcinoma, and malignant pleural mesothelioma." (PMID 31043167, 2019). "In this report, we demonstrate that depletion of SNW1 and its associating factor, EFTUD2, induced apoptosis in breast cancer cells." (PMID 25450007, 2015). "In this report, we demonstrate that depletion of SNW1, a component of the spliceosome, induces apoptosis in breast cancer cells." (PMID 25450007, 2015). "However, data supporting SNW1 up regulation in malignant tumors comes from breast cancer, hepatocellular carcinoma, bladder cancer and malignant pleural mesothelioma." (PMID 31043167, 2019). "It is proved that depletion of SNW domain containing 1 (SNW1) and its related factor EFTUD2 can induce breast cancer cell apoptosis." (PMID 32537629, 2020).
prostate carcinoma (3 papers, 2013 to 2025). A carcinoma that arises from epithelial cells of the prostate gland. "Overexpression of SNW1 has been confirmed to be associated with poor prognosis in various types of cancers, with upregulation observed in a subset of prostate cancer samples." (PMID 39968416, 2025). "Overexpression of SNW1 has been linked to adverse prognosis in different cancer types, but studies on the role of SNW1 in prostate cancer are lacking." (PMID 31043167, 2019).
microcephaly (1 paper, 2025). A congenital or acquired developmental disorder in which the circumference of the head is smaller than normal for the person's age and sex. "Here, we report that mutations in SNW1 impair interactions with core spliceosomal members, disrupt RNA splicing integrity, and result in microcephaly phenotypes in both humans and Drosophila." (PMID 40608414, 2025). "Since the loss of function of SNW1 in Drosophila results in a microcephaly phenotype similar to that observed in patients, we utilized human embryonic stem cell–derived (hESC-derived) cerebral organoid (hCO) models to unveil the functions of SNW1 in human brain development." (PMID 40608414, 2025).
neuroblastoma (1 paper, 2025). Neuroblastoma (NB) is the most common solid, extracranial childhood tumor. "In neuroblastoma, SNW1, a molecular chaperone, regulates the NOTCH pathway and correlates with poor prognosis." (PMID 40302793, 2025).
cancer (7 papers, 2015 to 2025). A tumor composed of atypical neoplastic, often pleomorphic cells that invade other tissues. "Our results suggest that the inhibition of SNW1 or its associating proteins may be a novel therapeutic strategy for cancer treatment." (PMID 25450007, 2015). "In module #36, SNW1 is a component of spliceosome in RNA splicing, its deletion can induce apoptosis, where the inhibition of SNW1 or its associating proteins may be a novel therapeutic strategy for cancer treatment." (PMID 30906311, 2019). "In conclusion, we propose the use of IPO8, PUM1, HNRNPL, SNW1 and CNOT4 as reference genes in studies comparing gene expression between different cancer and/or normal cell lines." (PMID 34593877, 2021). "Expression of other members of RQC including Pelota, SMG1 did not correlate across cancer types, nor were patterns observed in the expression of reference genes (GAPDH, HNRPL, PCBP1, SNW1, and RER1) identified to have stable expression patterns in human cancer and matching normal cell types." (PMID 38140537, 2023).
tumor (6 papers, 2015 to 2023). "In PNT1A (N) model, we found that the Menin tumor suppressor role is due to its interaction with the transcription factor SNW Domain Containing 1 (SNW1), which was previously reported to positively regulate the TGFb receptor signaling pathway, a key negative growth regulator in the normal prostate." (PMID 34711954, 2022). "Specifically, the splicing machinery components KHDRBS1, NOVA1, PRPF8, SNW1, SRSF1, SRSF10 and SRSF9 were overexpressed in tumor tissue." (PMID 38049848, 2023). "Interestingly, 16 of the 34 components examined (47.1%) were altered and, in line with our Discovery cohort, KHDRBS1, NOVA1, PRPF8, SNW1, SRSF1, and SRSF9 were also overexpressed in tumor tissue in this external cohort." (PMID 38049848, 2023).
SNW1 also shares sentences with these, for which no sentence is quoted: bladder cancer (2 papers); colorectal cancer (1); hepatocellular carcinoma (1); HIV-1 infection (1); malignant pleural mesothelioma (1); non-small cell lung carcinoma (1); renal carcinoma (1).